RNF213 (ring finger protein 213)
Diseases named in the same sentence as RNF213 in open-access papers (continued):
Sharing a sentence is not in itself a finding about the gene and the disease.
Moyamoya disease (continued). "In recent years, RNF213 has attracted attention mainly because studies have found that RNF213 is a susceptibility gene for moyamoya disease (MMD) in East Asian populations, especially in Japanese populations." (PMID 30671466, 2018). "The p.R4810K substitution in RNF213 has previously been linked to moyamoya disease in Asian populations." (PMID 30001348, 2018). "The RNF213 4950G>A genotype was more frequent in moyamoya disease (p = 0.008, GG vs. AA), with high frequencies of the RNF213 4950G>A polymorphisms in MMD." (PMID 29160859, 2017). "First, a question remains about how the p.R4810K variant or nine other variants impair the physiological function of RNF213, resulting in moyamoya disease." (PMID 29160859, 2017). "The ring finger protein 213 (RNF213) was identified as a susceptibility gene for moyamoya disease (MMD) recently." (PMID 29165136, 2017). "Moyamoya disease is often accompanied by hypertension, and a recent study suggested that a polymorphism of RNF213 is also associated with systolic blood pressure." (PMID 28778183, 2017). "Allele frequencies of 30 RNF213 variants in Korean patients with moyamoya disease and two population controls." (PMID 28617845, 2017). "We found a genetic cause of familial moyamoya disease in patient 25, who was heterozygote for the RNF213 p.D4013N mutation previously reported in familial moyamoya disease." (PMID 28750028, 2017). "In the present study, we screened for RNF213 variants in 19 Slovakian and Czech moyamoya disease patients." (PMID 27736983, 2016). "Although several monogenic diseases are known to be complicated by Moyamoya angiopathy, the ring finger protein 213 gene (RNF213) was identified as a susceptibility gene for MMD." (PMID 26662949, 2016). "We provide evidence suggesting, for the first time, the involvement of RNF213 in genetic susceptibility to moyamoya disease." (PMID 21799892, 2011). "Recently a significant association of a SNP in RNF213 with moyamoya disease in Japanese has been shown." (PMID 21799892, 2011). "Ss179362673 (p.R4810K in RNF213) was significantly associated with moyamoya disease, with a maximum odds ratio (OR) of 338.9 (P = 10−100)." (PMID 21799892, 2011). "First, we cannot provide evidence regarding impairment of physiological function of these variants of RNF213 in moyamoya disease." (PMID 21799892, 2011). "Taken together, these lines of evidence consistently support a conclusion that RNF213 is a susceptibility gene for moyamoya disease." (PMID 21799892, 2011). "Therefore, we conducted targeted gene analysis of RNF213 and other moyamoya angiopathy-related genes to elucidate the genetic factors associated with bypass development after combined bypass surgery." (PMID 38592555, 2025). "Additionally, another variant, RNF213 p.Ala5021Val, has been identified as a susceptibility factor for moyamoya disease in Chinese patients." (PMID 40869930, 2025). "Recent studies have suggested that RNF213, a known susceptibility gene for Moyamoya disease in East Asian populations, may also have immunological functions, including antimicrobial defense, via the ubiquitination of bacterial lipopolysaccharide." (PMID 41441210, 2025). "Given that chronic hypoperfusion and local hypoxia are hallmark features of Moyamoya disease, this mechanism may suggests that RNF213-driven inflammatory signaling under hypoxic conditions may contribute to vascular injury and remodeling in MMD." (PMID 41480156, 2025). "The RNF213 p.Arg4810Lys variant (c.14429G > A) is present in approximately 1.5% of healthy individuals in Japan and Korea, 0.5% in China, and 80% to 90% of familial moyamoya disease cases in Japan and Korea, as well as 20% to 30% of familial cases in China." (PMID 40869930, 2025). "Consequently, RNF213 ubiquitinates Cav-1 at several N-terminal lysine residues through K48 and K63 linkages, although several Moyamoya disease-associated RNF213 mutations greatly reduce this polyubiquitination." (PMID 40497951, 2025).
Moyamoya disease (continued). "Moyamoya disease (MMD) is primarily associated with genetic variants in RNF213." (PMID 40869987, 2025). "Clinical implications of RNF213 genetic variants, other than p.Arg4810Lys, in moyamoya disease (MMD), remain unclear." (PMID 37269436, 2024). "Cerebrovascular disorders, such as stroke and Moyamoya disease, have revealed specific genetic risk factors through GWAS, including the identification of 8 different loci causing neurological instability postischemic stroke and the strong association of the RNF213 locus with Moyamoya disease risk." (PMID 41341242, 2024). "While the precise function of RNF213 in Moyamoya disease remains to be identified, disturbances in substrate-induced oligomerization of RNF213 due to mutations in its E3 module may contribute to Moyamoya aetiology." (PMID 39375464, 2024). "In Moyamoya disease, a rare cerebrovascular condition, RNF213 mutations are common." (PMID 38136890, 2023). "In East Asians, cerebral autosomal dominant arteriopathy with subcortical infarcts and leukoencephalopathy (CADASIL) caused by NOTCH3 mutations, CADASIL2 and CARASIL (recessive) caused by HTRA1 mutations, and moyamoya disease (MD) caused by RNF213 mutations, are particularly prevalent." (PMID 36580209, 2023). "It is therefore unknown whether the RNF213 polymorphism in moyamoya disease is a function loss or function acquisition mutation." (PMID 36090342, 2022). "Since the penetrance of the RNF213 p.Arg4810Lys variant for moyamoya disease and PAH is quite low in human studies, the RNF213 p.Arg4810Lys variant is considered a susceptibility gene variant, and carriers may need a second-hit factor to develop vasculopathy." (PMID 35455046, 2022). "This gene was first recognized as a vasculopathy-susceptibility locus through genome-wide association studies undertaken in a Japanese population, demonstrating that heterozygotes for RNF213 p.Arg4810Lys (c.14429G>A, rs112735431) had a greatly increased risk of moyamoya disease." (PMID 35455046, 2022). "The presence of the RNF213 c.14429G>A (p.Arg4810Lys, rs112735431) mutation in patients with moyamoya disease has been implicated in earlier onset, increased risk of cerebral infarction as an initial presentation, and more frequent posterior cerebral artery (PCA) involvement." (PMID 34202349, 2021). "She had a heterozygous variant of RNF213, which is the susceptibility gene for moyamoya disease." (PMID 34858321, 2021). "Mutations in RNF213 predispose to Moyamoya disease (MMD), a rare cerebrovascular disorder." (PMID 34804992, 2021). "Here, we describe two children with moyamoya disease who also demonstrated kidney disease, elevated aminotransferases, and recurrent skin lesions found by exome sequencing to have de novo missense variants in RNF213." (PMID 33960657, 2021). "We have identified two patients with heterozygous de novo variants in RNF213 with severe, early‐onset moyamoya disease and stroke, but also with novel extra‐cerebral phenotypes, including chronic kidney disease, liver disease with elevated aminotransferases, and skin disease." (PMID 33960657, 2021). "Recent studies have implicated RNF213 mutations in the pathogenesis of moyamoya disease (MMD)." (PMID 31197213, 2019). "At least 24 genetic changes in the RNF213 gene have been associated with moyamoya disease." (PMID 29160859, 2017). "Although a founder variant of RNF213 4810G>A is a major genetic risk factor for moyamoya disease (MMD) in East Asians, the frequency and disease susceptibility of RNF213 variants remain largely unknown." (PMID 29160859, 2017). "Because most Japanese patients with moyamoya disease carry the p.R4810K variant of the ring finger 213 gene (RNF213), this may also be a risk factor for coronary artery disease; however, this possibility has never been tested." (PMID 28414759, 2017).
Moyamoya disease (continued). "Results from the present study identified RNF213 rare variants in 22.2% (4/18 probands) of Slovakian and Czech moyamoya disease patients, confirming that RNF213 may also be a major causative gene in a relative large population of white patients." (PMID 27736983, 2016). "This characteristic of moyamoya disease is in accordance with the notion that RNF213 is a susceptibility gene for moyamoya disease and reconciles our unexpected observation that this variant was found at an allele frequency of 1% in the Japanese, Korean and Chinese control populations." (PMID 21799892, 2011). "We next tested the association of RNF213 p.R4810K with moyamoya disease in East Asian populations." (PMID 21799892, 2011). "A question remains as to how the p.R4810K variant or other nine variants may impair the physiological function of RNF213 thereby resulting in moyamoya disease." (PMID 21799892, 2011). "In addition, the low identification rates of RNF213 variants in Caucasians compared with East Asians strongly suggests that there is genetic heterogeneity of moyamoya disease between these two populations." (PMID 21799892, 2011). "We concluded that RNF213 is a susceptibility gene for moyamoya disease." (PMID 21799892, 2011). "Although genetic testing for RNF213 variants was not performed in this case due to facility limitations, genetic testing for RNF213 variants, which are strongly associated with moyamoya disease in East Asian populations, may provide insights into any underlying genetic predisposition." (PMID 41441210, 2025). "RNF213 variants might play a role in moyamoya disease in PHACE syndrome." (PMID 40624699, 2025). "However, recent studies suggest that RNF213 mutations may affect lipid droplet targeting and impair fat-stabilizing activity, leading to a focus on lipid metabolism as a key factor in Moyamoya disease development." (PMID 38167529, 2024). "This gene was first recognized as a vasculopathy-susceptibility locus in 2011 through the genome-wide linkage analysis of Japanese families with moyamoya disease, which demonstrated that heterozygotes for RNF213 p.Arg4810Lys (c.14429G>A, rs112735431) might be susceptible to moyamoya disease." (PMID 35455046, 2022). "RNF213 is a susceptibility gene for moyamoya disease, yet its exact functions remain unclear." (PMID 29483617, 2018). "Interestingly, the G-G-A-G (p = 0.005), G-A-G-G (p < 0.0001), and G-A-A-G (p = 0.033) (RNF213 4448/4810/4863/4950) haplotypes were associated with moyamoya disease risk in the pediatric group whereas G-A-G-A (p < 0.0001) elevated moyamoya disease risk in the adult group." (PMID 29160859, 2017). "Our results show that polymorphism of RNF213 4810G>A and 4950G>A are associated with the occurrence of moyamoya disease, and that 4810G>A may affect the general moyamoya prevalence, while 4950G>A is particularly relevant to the occurrence of moyamoya in the adult group." (PMID 29160859, 2017). "Therefore, RNF213 is very likely to be a bona fide susceptibility gene for moyamoya disease." (PMID 21799892, 2011). "Although further studies are necessary to clarify the biochemical function and pathological role of RNF213 in moyamoya disease, the discoveries of its association with the disease and its unique roles in angiogenesis may pave a way to early diagnosis and prevention." (PMID 21799892, 2011). "Our study principally provides a deeper understanding of the function of RNF213 and reveals potential therapeutic targets against bacterial brain infection and moyamoya disease." (PMID 40623121, 2025). "In this study, we performed WES and targeted analyses for RNF213 as well as previously reported moyamoya angiopathy-related genes." (PMID 38592555, 2025). "We analyzed RNF213 and 36 other moyamoya angiopathy-related genes by whole-exome sequencing and extracted rare or damaging variants." (PMID 38592555, 2025).
Moyamoya disease (continued). "RNF213, one of the most reliable moyamoya-related genes, has been reported to be closely related to angiogenesis in moyamoya disease." (PMID 40722175, 2025). "Despite the presence of the RNF213 gene, only imaging can confirm the diagnosis of Moyamoya disease." (PMID 40895857, 2025). "RVs and DVs were extracted from the WES results based on the earlier definitions and focusing on RNF213 as well as the other 36 moyamoya angiopathy-related genes." (PMID 38592555, 2025). "Our study provides a deeper understanding of the function of RNF213 and reveals potential therapeutic targets against bacterial brain infection and moyamoya disease." (PMID 40623121, 2025). "Our findings elucidate the potential functions of the RNF213–mediated BBB integrity by targeting TRAF3 for the regulation of IFN-I signaling in moyamoya disease development." (PMID 40623121, 2025). "In targeted gene analysis, including previously reported moyamoya angiopathy-related genes, RNF213 was identified as the most influential gene related to postoperative DTA development." (PMID 38592555, 2025). "Added to these similarities, some TKI-associated CVS was reported to be affected by the genetical abnormality (ring finger protein 213) of moyamoya disease." (PMID 41542274, 2024). "Initially identified in 2011 as the major susceptibility gene for Moyamoya disease (MMD), a rare cerebrovascular disorder characterized by progressive stenosis of intracranial arteries, RNF213 has since been implicated in various subtypes of ischemic stroke." (PMID 39857601, 2024). "Remarkably, FLNA has been recently identified as a possible second-hit gene promoting moyamoya disease-like vascular formation in a PVNH patient, and it was associated with Ring Finger protein 213 (RNF213) p.R4810K variant, the most common MMA polymorphism." (PMID 37446373, 2023). "Although little is known about the biological function of RNF213 or its related pathogenesis in moyamoya disease, the identification of RNF213 as an immunosensor reveals a clear molecular link between MMD and infection." (PMID 37153657, 2023). "This article reviews the latest research progress in epidemiology, RNF213 gene, pathomorphology, clinical characteristics and treatment of moyamoya disease combined with renovascular hypertension, in order to provide reference for clinical workers." (PMID 36090342, 2022). "We have reported on a family with the RNF213 p.Arg4810Lys variant in which the mother had PAH and her daughter developed moyamoya disease." (PMID 35455046, 2022). "Furthermore, co-occurrent cases of moyamoya disease with retinal vessel occlusion, carotid artery stenosis, and renal artery stenosis have been identified, suggesting that these vascular diseases may be associated with RNF213 variants (highlighted in black)." (PMID 35455046, 2022). "We also reported one family with the RNF213 p.Arg4810Lys variant in which the mother developed pulmonary arterial hypertension (PAH), and her daughter had moyamoya disease." (PMID 35455046, 2022). "Multiple reports with increasing evidence have been published linking Moyamoya disease to the ring finger protein 213 gene." (PMID 36482624, 2022). "The ring finger protein 213 (RNF213) susceptibility gene has been detected in more than 80% of Japanese and Korean patients with moyamoya disease (MMD), a bilateral internal carotid artery (ICA) occlusion." (PMID 34773068, 2021). "RING finger protein 213 (RNF213) is a susceptibility gene for large artery atherosclerosis (LAA) as well as moyamoya disease (MMD), which is a progressive steno-occlusive disease of the circle of Willis." (PMID 34335228, 2021). "The presented cryo-EM structure now provides a precise roadmap to dissect the role of RNF213 in vascular formation and the connected Moyamoya disease." (PMID 32573437, 2020). "Elevated activity of the Wnt/Ca2+ pathway has also been observed in patients with Moyamoya disease (MMD), which is caused by missense mutations in RNF213." (PMID 31170158, 2019).
Moyamoya disease (continued). "In a subgroup analysis, the RNF213 4810G>A was more frequent in moyamoya disease, and the comparison with GG+AA genotype was also significantly different in moyamoya patients." (PMID 29160859, 2017). "In subgroup analyses, the GA genotype of the RNF213 4810GA was more frequent in moyamoya disease (p < 0.001; GG vs. AA) and the comparison with the GG+AA genotype was also significantly different in moyamoya patients." (PMID 29160859, 2017). "A total of 69 RNF213 coding exons were directly sequenced in 18 probands and one relative who suffered from moyamoya disease in Slovakia and the Czech Republic." (PMID 27736983, 2016). "RNF213 gene is involved in the pathogenesis of moyamoya disease which has been reported to be both congenital and acquired." (PMID 28324520, 2015). "RNF213 encodes a unique protein with AAA+ ATPase and E3 ubiquitin ligase activities that are critical for its diverse roles, which range from involvement in human vasculopathies, such as Moyamoya disease, to ubiquitination of viral and bacterial pathogens." (PMID 40497951, 2025). "Furthermore, we analyzed potential genes other than RNF213 that were related to moyamoya angiopathy." (PMID 38592555, 2025). "The first patient carried the RNF213 p.R4810K variant, the susceptibility variant of moyamoya disease in the Asian population, but the second patient did not have any variant in this gene." (PMID 40799876, 2025). "The study of genes associated with moyamoya disease (MMD; except RNF213)." (PMID 39822761, 2025). "RNF213 and GUCY1A3 are regarded as potential pathogenic genes for Moyamoya disease." (PMID 40722175, 2025). "In addition, the role of RNF213 in moyamoya disease and other cerebrovascular disorders, particularly in East Asian populations, has been elucidated." (PMID 39858606, 2025). "Additionally, RNF213 knockdown disrupts angiogenesis and sensitizes endothelial cells to inflammation, leading to altered angiogenesis and potential links to Moyamoya disease." (PMID 39869563, 2025). "In addition, as the most potential susceptibility gene of moyamoya disease, the mechanism of RNF213 (Ring Finger Protein 213) in moyamoya disease is still being explored." (PMID 38704490, 2024). "Using exome sequencing, the presence of multifocal FMD was associated to myosin light chain kinase (MYLK – also involved in thoracic aneurysms), dynein cytoplasmic heavy chain 1 (DYNC2H1), sarcomeric protein obscuring (OBSCN), and RNF213 (involved in Moyamoya disease) genes." (PMID 37214559, 2023). "The absence of the RNF213 p.R4810K variant has been suggested as a possible novel biomarker for identifying severe forms of childhood moyamoya disease." (PMID 36090342, 2022). "Neither did the mutations in RNF213 that are associated with the moyamoya disease patients cause defect in LPS ubiquitylation." (PMID 34881292, 2021). "RNF213 has mainly been studied in the context of Moyamoya disease (MMD)." (PMID 34804992, 2021). "A previous study, which investigated the moyamoya disease susceptibility polymorphisms, reported that p.R4810K in RNF213 was found in the East Asian population but not in Southeast Asians." (PMID 32854392, 2020). "Recent studies have suggested that variants of RNF213, a susceptibility gene for moyamoya disease (MMD), are also related to non-MMD ICASO." (PMID 32182997, 2020). "Scientists still need more detailed information on RNF213’s structure and chemical activity before we can understand what the mutant protein might be doing in Moyamoya disease." (PMID 32573437, 2020). "Recently, several studies indicated the c.14576G>A variant on the ring finger protein 213 (RNF213), a founder variant of moyamoya diseases (MMD), was associated with non-MMD intracranial major artery stenosis/occlusion (non-MMD ICASO)." (PMID 30992731, 2019). "IV.4 and IV.17 did not share any of the common or rare variants in RNF213 already associated with moyamoya angiopathy." (PMID 30001348, 2018).